HIF3A (hypoxia inducible factor 3 subunit alpha)
Diseases named in the same sentence as HIF3A in open-access papers (continued):
Sharing a sentence is not in itself a finding about the gene and the disease.
tumor (continued). "In addition, HIF-1α and HIF-3α nuclear expression levels were significantly associated with CSS in patients with ccRCC in univariate analysis but not HIF-2 α, implying that the major HIF-α proteins have different biological features that are crucial for tumor progression." (PMID 38571885, 2024). "Parkin negatively regulates the expression of HIF-1α and HIF-3α in GBM under hypoxic conditions, resulting in reduced expression of pro-angiogenic factors and tumor invasiveness." (PMID 36980235, 2023). "It has been shown before that ectopic expression of HIF3A results in down-regulation of VEGF and results in reduced vascular density of tumors and slower tumor growth in vivo." (PMID 25129238, 2014). "Notably, transcriptomic data and RTqPCR results demonstrated that while PUM2 and HIF3A were highly expressed in normal tissues, DDB1 showed increased expression in tumor tissues, with CUL1, COPS2, and UBE2D3 remaining unchanged." (PMID 40524221, 2025). "The expression levels of nuclear HIF-1α, HIF-2α, and HIF-3α in ccRCC did not vary based on age, gender (data not shown) or between tumor grade in ccRCC." (PMID 38571885, 2024). "At the same time, Vegf expression increased only in the tumor tissue of the SH animals relative to the control, and no changes in Hif1a, Epas1, or Hif3a expression were noted either in the tumor tissues or in the peritumoral area." (PMID 39063041, 2024). "Similarly, the expression of HIF3A mRNA was significantly diminished in the tumor tissues of 62 LUSC patients, and HIF3A mRNA expression was significantly lower in plasma samples from 103 LUAD patients and 96 LUSC patients compared with healthy recruits." (PMID 34245041, 2021). "Some of these genes, which interfere with tumor cell growth/differentiation/migration/invasion (such as MYC, MET, PROM1, and PTK2), induce hypoxia (such as ARNT2, HIF3A, TGB2, MMP2, and POSTN) and genes regulating transcription via acetylation were downregulated upon pembrolizumab treatment." (PMID 32616706, 2020). "HIF-1α and HIF-2α contribute to tumor progression, whereas HIF-3α is a negative controller of HIF-1α, while the role of HIF-3a on the endogenous feedback regulatory loop under hypoxia is not well determined yet." (PMID 29953500, 2018). "Notably, hypoxic tumor volume was negatively correlated with immunohistochemistry, which might be due to the feedback mechanism that occurred between HIF-1α and markers or genes of the tumor, or the presence of the other isoforms of HIF-1α, such as HIF-2α and HIF-3α." (PMID 37445730, 2023). "Transcriptomic data and RT-qPCR findings indicated that PUM2 and HIF3A exhibited high expression levels in normal tissues, while DDB1 showed increased expression in tumor tissues; no significant changes were observed for CUL1, COPS2, and UBE2D3." (PMID 40524221, 2025). "Additionally, there was a significant correlation between nuclear HIF-2α expression and tumor size (P = 0.035), whereas not with HIF-1α (P = 0.106) and HIF-3α (P = 0.701)." (PMID 38571885, 2024).
cancer (28 papers, 2014 to 2026). A tumor composed of atypical neoplastic, often pleomorphic cells that invade other tissues. "In patients with ccRCC, the nuclear expressions of HIF-1α and HIF-3α was significantly associated with cancer-specific survival (CSS) in univariate analysis." (PMID 38571885, 2024). "For example, HIF3A, which is reported to promote the cancer metastatic phenotype, was observed to be highly linked with PI3K pathway activation across multiple cancer types." (PMID 33299416, 2020). "This link between HIF-3 and lipid metabolism may also explain why only a few cancer cell lines express the long HIF3A splice variants, whereas the HIF-1α that drives glucose metabolism is their major HIF form." (PMID 31768607, 2020). "Thus, HIF3A may exist in the lung epithelium and play a role in the hypoxic environment of cancer cells or adjacent normal cells, in association with other targeted genes." (PMID 34245041, 2021). "The specific regulatory roles of HIF-2α and HIF-3α in breast cancer are also briefly discussed in this review, which highlights how hypoxia activates downstream signaling pathways, creating a pro-cancer loop with the HIF–ncRNA regulation network." (PMID 41614928, 2026). "Hypoxia is known to promote cancer development, and aberrant expression of hypoxia-inducible factor 3 subunit alpha (HIF-3α) has been shown to accelerate cancer development and contribute to poor disease outcomes." (PMID 39736850, 2025). "HIFs, such as HIF1α, HIF2α, and HIF3α, binds to the target gene promoter to promote its transcription, thus accelerating cancer cell migration, proliferation, and invasion." (PMID 35635094, 2022). "Studies are needed to further explore the contribution of miR-630 to prognosis by regulating the expression of HIF-1α and HIF-3α and by modulating cancer hallmarks of HeLa cells." (PMID 36277475, 2022). "Some HIFs, such as HIF1A, ARNT, EPAS1, and HIF3A, were linked with unfavorable outcomes for pan-cancer, while two HIFs including ARNTL and ARNT2 were associated with favorable outcomes in pan-cancer." (PMID 33299416, 2020). "Additional studies will be necessary to clarify the exact role of HIF3α in different normal and cancer cells and in different growth conditions; the newly CRISPR/CAS technology will help us to better define its role." (PMID 29643458, 2018). "The human Hif3A has 19 transcripts in total, of which only 6 experimentally validated in different mammalian cells, including cancer cells." (PMID 29643458, 2018). "Given that HIF3A is highly expressed in alveolar epithelial cells and thought to protect cells from hypoxia-induced damage, it is tempting to speculate that its inactivation may predispose cells to DNA damage, contributing to the onset of lung dysplasia and carcinoma." (PMID 29262847, 2017). "We examined a cohort of 416 CRC patients from a TCGA dataset and found that all transcripts except HIF3A mRNA were significantly elevated in cancer tissue compared to expression levels in normal tissues." (PMID 26244988, 2015). "HIF-3α is less studied, and it has been shown to play a role in cancer cell invasion and migration." (PMID 37886168, 2023). "Upregulating HIF-3α can greatly activate the cancer development-related genes." (PMID 36277475, 2022). "We also found that HIF-3α cooperates in the expression of cancer cell transcriptome." (PMID 36277475, 2022). "Overexpression of miR-210 in cancer cells may contribute to a persistent function of HIF-1α by regulating HIF-3α and other targets, leading to the progression of the cancer by attenuating cell proliferation and increasing drug resistance." (PMID 29953500, 2018). "HIF3A could act as a novel target to be comprehensively studied in hypoxic cancer biology." (PMID 34245041, 2021).
cancer (continued). "Similarly, a previous study reported that variants of HIF3A were detected at an identifiable level in the cDNA panels of cancer cells and subsequently showed that the HIF3A‐based three alternative first exons were discovered at a downgraded extent in multiple cancer cell lines." (PMID 34245041, 2021). "The exact molecular mechanisms of HIF3A in human cancer, specifically in NSCLC, remain unknown." (PMID 34245041, 2021). "The target genes of HIF-1α and HIF-2α are thought to be negatively regulated by HIF-3α, and the HIF-1α subunit, in particular, is essential for the development of cancer." (PMID 41614928, 2026). "We further explored the effect of 5 hub genes (ACSL4, FANCD2, HIF3A, HSPA5, and PSMB7) in 33 kinds of cancer in the TCGA database." (PMID 35652069, 2022). "Among them, HIF3A and EPAS1 are significantly downregulated, whereas ATNTL and ARNT2 show minimal expression changes in most cancer types." (PMID 33299416, 2020). "However recent work evaluated the expression levels of HIF-3α in various types of cancer, and interestingly found that in contrast to HIF-1α and HIF-2α, an increase in expression levels of HIF-3α correlated with better survival." (PMID 37886168, 2023). "Human HIF3A may play an opposing role to HIF‐1 and HIF‐2, which have a significant role in the development and progression of cancers." (PMID 34245041, 2021). "HIF3α activation is cell specific and does not appear to be related to cancer cell aggressiveness." (PMID 24801981, 2014). "Even though HIF-1α and HIF-2α are dominantly expressed in cancer cells, our present data could not exclude that the HIF-3α was also involved in PIM2 regulation." (PMID 24505470, 2014).
metabolic disease (3 papers, 2016 to 2023). A congenital disorder (due to inherited enzyme abnormality) or acquired (due to failure of a metabolically important organ) disorder resulting from an abnormal metabolic process. "Further studies are needed to increase our understanding of the role of HIF3A in metabolic disease." (PMID 27594926, 2016). "Thus, Hif3α is a regulator of BAT induction, guiding beneficial metabolic reprogramming, dissipating energy as heat thereby improving glucose and lipid metabolism, decreasing the insurgence of metabolic disorders." (PMID 35096807, 2021).
neurodegenerative disease (3 papers, 2015 to 2025). A disorder of the central nervous system characterized by gradual and progressive loss of neural tissue and neurologic function. "It suggested that Hif3a was not only a potential target of DMDD to protect neurons from damage, but also a diagnostic biomarker of neurodegenerative disease." (PMID 34975464, 2021). "Studies found that Hif3α might play key roles in neurodegenerative diseases, including diabetic cognitive impairment and AD-like phenotype in gene knockdown models." (PMID 40243952, 2025). "However, the particular molecular mechanism related to Hif3α’s role in AD and other neurodegenerative diseases remains underexplored." (PMID 40243952, 2025).
Neurological Diseases (2 papers, 2019 to 2023). "Gene networks enriched with the adult CpG list included a network featuring upregulation of the gene HIF3A and downregulated Akt, which was enriched in genes associated with Hereditary Disorders, Neurological Diseases and Organismal Injuries and Abnormalities." (PMID 36959629, 2023).
lung (1 paper, 2015). "These functions of the HIF-3α, thus suggests that it can potentially play a role in mediation of lung carcinogenesis." (PMID 25820198, 2015).
respiratory diseases (1 paper, 2025). "Previously identified smoking-related CpG sites that were also linked to smoky coal combustion – annotated to genes such as AHRR, SNORD93, NWD1, EDC3, STK24, ZDHHC14, HIF3A – converge on key pathways involved in pollutant response, respiratory diseases, and carcinogenesis." (PMID 40236422, 2025).
HIF3A also shares sentences with these, for which no sentence is quoted: cholangiocarcinoma (2 papers); adenocarcinoma (1); alcohol dependence (1); Ataxia (1); carotid atherosclerosis (1); diabetic retinopathy (1); dilated cardiomyopathy (1); head and neck cancer (1); hypertrophic cardiomyopathy (1); hypoplastic left heart syndrome (1); hypothyroidism (1); infection (1); lung carcinoma (1); meningioma (1); multiple sclerosis (1); osteosarcoma (1); ovarian carcinoma (1); Parkinson disease (1); pulmonary hypertension (1); schizophrenia (1); Sleep apnea (1); type 2 diabetes (1); uterine cancer (1).